SOCS3 (suppressor of cytokine signaling 3)
Diseases named in the same sentence as SOCS3 in open-access papers (continued):
Sharing a sentence is not in itself a finding about the gene and the disease.
colorectal cancer (25 papers, 2016 to 2025). A primary or metastatic malignant neoplasm that affects the colon or rectum. "The purpose of the study was to explore the role of SOCS3 in colorectal carcinoma and its underlying mechanisms." (PMID 29662621, 2018). "SOCS3 has been observed during angiogenesis as a negative regulator from studies of both human small cell lung cancer and colorectal cancers, while dysregulation of SOCS3 gene expression has been associated with both CAD and related conditions including acute coronary syndrome." (PMID 40883367, 2025). "In colorectal cancer, STAT5 overexpression has been associated with a poor prognostic outcome where IL-23 signaling inhibits the expression of SOCS3, an inhibitor of STATs expression and activation." (PMID 40176914, 2025). "As an important tumor suppressor, SOCS3 disfunction plays a catalytic role in the occurrence, progression, and metastasis of various tumors, such as colorectal cancer, gastric cancer, and thyroid cancer." (PMID 38533493, 2024). "This study suggested that miR-92a functions as an oncogene of CRC through mediating the stemness of colorectal cancer cells by directly binding and repressing SOCS3." (PMID 35184640, 2022). "suggest that miR-4449 promotes colorectal cancer cell proliferation via regulation of SOCS3/STAT3 signaling pathway." (PMID 35780119, 2022). "Experiments above elucidate the effect of miR-92a/SOCS3 on the malignant behavior of colorectal cancer cells." (PMID 35184640, 2022). "Aberrant expression of SOCS1 and SOCS3 has been described in human colorectal cancer, where SOCS3 overexpression inhibits proliferation, migration and invasiveness of tumor cells, while SOCS1 overexpression has pro-oncogenic activity." (PMID 35413796, 2022). "MiR-4449 promoted cell proliferation and JAK2/STAT3 signaling activity by inhibiting SOCS3 in colorectal cancer." (PMID 34691358, 2021). "A stably transfected colorectal carcinoma cell line (8348SOCS3) with high expression of SOCS3 was established." (PMID 29662621, 2018). "SOCS3 expression was significantly lower in colorectal carcinoma tissue than in normal colorectal mucosa, and was negatively correlated with tumor invasion depth, lymph node metastasis, differentiation degree, and TNM stage." (PMID 29662621, 2018). "Protein and mRNA expression of SOCS3 in colorectal carcinoma and normal colorectal mucosa was detected using immunohistochemistry and real-time quantitative PCR." (PMID 29662621, 2018). "Bioinformatics analysis demonstrated that high SOCS3 expression affected multiple signaling pathways in colorectal carcinoma including TGF-β/Smads, NF-κB, and HIF-MAPK pathways." (PMID 29662621, 2018). "The effects of SOCS3 overexpression on the growth, proliferation, invasion and tumor formation of colorectal carcinoma cells were examined by CCK-8 assay, transwell method and tumorigenicity assays in nude mice." (PMID 29662621, 2018). "TSA increases the expression of SOCS1 and SOCS3 in human colorectal cancer cells and suppresses CRC growth." (PMID 28228755, 2017). "Trichostatin A (TSA), a histone deacetylase inhibitor, suppresses JAK2/STAT3 signaling by increasing the expression of SOCS1 and SOCS3 in human colorectal cancer cells and manipulates the expression of SOCS proteins in tumors." (PMID 28228755, 2017). "Moreover, trichostatin A (TSA) leads to the hyperacetylation of histones associated with SOCS1 and SOCS3 promoters, which significantly downregulates JAK2/STAT3 signaling in colorectal cancer cells." (PMID 35611249, 2022). "We found that breast and ovarian cancer patients with high expression levels of SOCS3 were resistant to chemotherapy; however, GBM and colorectal cancer patients with high expression levels of SOCS3 were more sensitive to chemotherapy than patients with low SOCS3 expression." (PMID 35600392, 2022). "SOCS3 protein may be a useful indicator for malignancy and prognosis of colorectal carcinoma and also a new target for gene therapy." (PMID 29662621, 2018).
colorectal cancer (continued). "Furthermore, the effect of SOCS3 overexpression on the gene expression profile of colorectal carcinoma cells was analyzed using human genome arrays." (PMID 29662621, 2018). "However, the relationship of SOCS3 with colorectal carcinoma remains poorly understood." (PMID 29662621, 2018). "In colorectal cancer, NR1H4 activation suppresses the JAK2/STAT3 signaling pathway via trans-activation of the suppressor of cytokine signaling 3 (SOCS3) gene and antagonizes Wnt/β-Catenin signaling, acting as a tumor suppressor." (PMID 40656893, 2025). "Similar to our result, other researchers have indicated that histone deacetylase inhibitor TSA suppresses the growth of colorectal cancer cells, and induces apoptosis through SOCS1 and SOCS3 upregulation and JAK2/STAT3 signaling inhibition." (PMID 34319031, 2021). "Previous studies in myeloproliferative neoplasms and colorectal cancer, indicated that TSA treatment increases the SOCS3 expression, and this increase repressed the cell growth in both type of cancers." (PMID 30811476, 2019). "Additionally, miR-708 enhances STAT3 activation by targeting the 3’UTR of SOCS3, and the decreased expression of MEG3 in colorectal cancer (CRC) tissues and cells leads to a reduction in SOCS3 levels, promoting the malignant proliferation of colon stem cells and CRC cell lines." (PMID 39830506, 2024).
colon carcinoma (23 papers, 2014 to 2024). "It has been shown that the activity of the Janus tyrosine kinases/signal and activator of transcription (JAK/STAT) pathway is strongly associated with colon cancer, where the suppressor of cytokine signaling-3 (SOCS3) negatively regulates the JAK/STAT pathway." (PMID 36278234, 2022). "In addition, miR-708 deficiency attenuated colon tumor development and colonic organoid growth via direct targeting of SOCS3 accumulation." (PMID 34934045, 2021). "The STAT3-mediated increase in TNFR2 expression on colon cancer cell lines was reduced by SOCS3, a cytokine-inducible STAT3 inhibitor." (PMID 36765633, 2023). "Previously, we reported that valproic acid upregulated SOCS-1 and SOCS-3 gene expression in colon carcinoma SW48 cell line." (PMID 35611249, 2022). "Previously, we reported that the histone deacetylase inhibitor valproic acid can reactivate silenced SOCS-1 and SOCS-3, resulting in apoptosis induction in the colon carcinoma SW48 cell line." (PMID 35611249, 2022). "Inconsistently, our previous work indicated that valproic acid and zebularine can up-regulate SOCS-1 and SOCS-3 gene expression leads to cell growth inhibition in the colon carcinoma SW48 cell line." (PMID 34319031, 2021). "USP25 is also involved in the immune regulation of colon tumors and intestinal bacterial infections by regulating the levels of Wnt and suppressor of cytokine signaling 3 (SOCS3)." (PMID 35096833, 2021). "All of these results indicate that FXR activation inhibits JAK2/STAT3 pathway by regulating SOCS3 transcription in colon cancer cells." (PMID 33164339, 2020). "Conversely, IEC-specific Socs3 ablation or expression of the SOCS3-binding deficient gp130Y757F mutation both inducing STAT3 activation, promoted colonic tumor growth and incidence." (PMID 27582544, 2016). "Increasing evidences have displayed over-expression of SOCS3 exhibited preclinical anti-tumor activity against HCC, malignant pleural mesotheliom and inflammation-associated colon cancer." (PMID 26416445, 2015). "Similar epigenetic silencing of SOCS3 has been seen in cholangiocarcinoma and colonic cancer, resulting in enhanced IL-6/STAT3 signalling and reduced apoptosis." (PMID 24757565, 2014). "SOCS3 silencing has been reported to increase the expression of c-Myc and tumorigenesis, and accordingly, its expression has been found to be lower in breast, ovarian, and colon cancers and glioblastoma in comparison with tumor-adjacent tissues." (PMID 38534772, 2024). "Interestingly, SOCS3 showed two completely different trends in liver metastases and lung metastases in colon cancer patients." (PMID 37025997, 2023). "Interestingly, four genes that were originally highly expressed in the high SOCS3 expression group in colon cancer became low expressed after lung metastasis, including TTC40, PCDHA2, SP3P and ZNF471." (PMID 37025997, 2023). "These suggested that SOCS3 might be involved in the process of lung metastasis in colon cancer patients through its interaction with macrophages." (PMID 37025997, 2023). "Besides, we performed immunohistochemistry (IHC) staining in colon cancer patients with lung metastasis to explore the relationship between SOCS3 status and macrophage infiltration and tumor metastasis." (PMID 37025997, 2023). "Based on existing studies of SOCS3 in immune response and its prominent association with immune response in COAD, we explored SOCS3 status and macrophage infiltration in colon cancer patients and the differences in the primary focus and lung metastases of colon cancer." (PMID 37025997, 2023). "High SOCS3 expression was more inclined to poor prognosis and was positively correlated with main immune cell infiltration in almost each cancer type, especially in colon cancer." (PMID 37025997, 2023).
colon carcinoma (continued). "Meanwhile, our research gave a new perspective on the relationship between SOCS3 status and macrophage infiltration in colon cancer patients with lung metastasis, which provided support for the possibility of SOCS3 as a potential target of tumor progression and tumor immunotherapy in colon cancer." (PMID 37025997, 2023). "Low expression of Socs3 and Tcf3 have been associated with the occurrence and progression of CRC, while upregulation of Fas and Il15 is associated with malignant potential in colon cancer cells by promoting tumor motility and metastasis." (PMID 34843459, 2021). "Taken together, these results suggest that FXR activation might suppress JAK2/STAT3 pathway in colon cancer cells by up‐regulating SOCS3 expression." (PMID 33164339, 2020). "Interestingly, AvrA activates the expression of the STAT3 target genes MMP7 (matrix metalloproteinase-7) and SOCS3 (suppressor of cytokine signaling 3) in a colon cancer mouse model." (PMID 31611869, 2019). "Indeed, this idea is supported by a previous study that showed that SOCS3 overexpression in a colon cancer cell line inhibits subsequent TNF-induced p65 phosphorylation." (PMID 28193827, 2017). "SOCS3 possessed value as a prognostic marker and target for immunotherapeutic intervention in different tumors and might be a potential target of tumor progression and tumor immunotherapy in colon cancer." (PMID 37025997, 2023). "To explore the molecular mechanisms of SOCS3 in lung metastasis, we divided the colon cancer and lung metastasis patients into two groups in the GSE68468 dataset respectively via the median of SOCS3." (PMID 37025997, 2023). "Samples and corresponding clinical information of 32 colon cancer patients with lung metastasis were collected, and the CD68, CD163, and SOCS3 status were conducted using immunohistochemistry (IHC)." (PMID 37025997, 2023). "The current study aimed to investigate the effect of valproic acid (VPA) on SOCS-1, SOCS-2, SOCS-3, SOCS-5, SOCS6, and SOCS-7 gene expression and cell growth inhibition in colon carcinoma IS1, IS2, and IS3 cell lines." (PMID 35611249, 2022). "As we previously showed in a murine colon cancer cachexia model, there was an induction of IL6 and Socs3 mRNA expression with a decrease in Lep mRNA expression in epididymal white adipose tissue." (PMID 35785158, 2022). "To further validate the involvement of SOCS3 in OCA‐mediated inhibition of JAK/STAT signalling, we knocked down SOCS3 in colon cancer cells." (PMID 33164339, 2020). "In the present study, the FXR agonist OCA inhibited colon cancer cell proliferation and invasion by repressing JAK2/STAT3 pathway via regulating SOCS3 transcription." (PMID 33164339, 2020). "Similar to SOCS1 and SHP1, STAT6high HT-29 cells expressed low constitutive mRNA of SOCS3 and SOCS7 than STAT6null colonic cancer Caco-2 cells." (PMID 24757565, 2014). "In colon cancer, HABP3 is a common overregulated gene that might be involved in the interaction with SOCS3 and the expression of IFN-stimulated genes." (PMID 39228892, 2024). "This includes the miR-221-3p released by the human colon cancer HCT-116 cells that triggers the proliferation, migration and tubulogenesis of endothelial cells through the depletion of SOCS3 (suppressor of cytokine signaling 3) transcripts and the subsequent upregulation of VEGFR." (PMID 36831450, 2023). "The results of the current study demonstrate that VPA plays its role through the upregulation of SOCS-1, SOCS-2, SOCS-3, SOCS-5, SOCS6, and SOCS-7 genes, resulting in cell growth inhibition and apoptosis induction in colon carcinoma IS1, IS2, and IS3 cell lines." (PMID 35611249, 2022). "Importantly, Meg3 acts as a ceRNA for miR-708, leading to enhanced expression of SOCS3, which in turn suppresses STAT3 signaling and malignant proliferation of colonic stem cells during the early stage of colon tumor formation." (PMID 34934045, 2021).
colon carcinoma (continued). "The overexpression of miR-19b in human colon cancer cell line HT-29 cells downregulates the protein level of SOCS3, but not that of the SOCS3 mRNA." (PMID 28228755, 2017). "Furthermore, in colonic cancer cell line HT-29 that constitutively expresses STAT6, there is downregulation of CIS and SOCS7 (in addition to SOCS1, SOCS3, and SHP1)." (PMID 24757565, 2014).
COVID-19 (23 papers, 2020 to 2025). A disease caused by infection with severe acute respiratory syndrome coronavirus 2. "The decreased expression of SOCS3 in the non survivors suggest a failed attempt of NK cells to mitigate the inflammatory damage associated with severe COVID-19." (PMID 39928675, 2025). "In contrast, cross-sectional analysis shows that ISG expression is deficient and IFN suppressors such as SOCS3 are upregulated in severe and critical COVID-19." (PMID 38238298, 2024). "The increased expression of OAS1, MAVS and SOCS3 mRNA in COVID-19 was consistent for both active and recovered cases." (PMID 41468475, 2025). "Whilst mRNA levels of IFN- γ, IFN-1α, MAVS, IL-6, SOCS1 and SOCS3 were similar between LTBi positive individuals in the HC and COVID-19 groups." (PMID 41468475, 2025). "In summary, SOCS3 upregulation is a consistent feature of severe and critical COVID-19, across multiple cohorts, both in peripheral blood and at sites of infection." (PMID 38238298, 2024). "COBL, GPX3 and SOCS3 were lower in the early and late secretory phase in women with COVID-19, whereas DOCK2 and SLC2A3 were unchanged." (PMID 38372528, 2024). "We have also shown that the IFN suppressor SOCS3 is upregulated in blood and airway in severe COVID-19, and that its inhibition substantially attenuates SARS-CoV-2 replication in vitro." (PMID 38238298, 2024). "The myocardial injury caused by COVID-19 was associated with multiple inflammatory pathways, and IL6, NFKBIA, CSF1, CXCL1, IL1R1, SOCS3, and CASP1 were key genes of the inflammatory pathway." (PMID 37564653, 2023). "The overexpression of some of these biomarkers was similarly observed in the blood serum of severe COVID-19 patients with extrapulmonary dysfunction (e.g. SOCS3 and TRIM56)." (PMID 34262555, 2021). "RT-qPCR revealed significantly reduced SOCS3 mRNA in spike S2-expressing cells, implying enhanced IL-6 signaling which is a key part of the cytokine storm occurring in severe COVID-19." (PMID 34073047, 2021). "We determined the association between LTBi positivity with severity of COVID-19 as well as mRNA expression of immune related genes including those required for MTB as well as SARS-CoV-2 control; IFN-γ, IFN-α, IL-6, IL-10, OAS1, MAVS, SOCS1 and SOCS3 molecules." (PMID 41468475, 2025). "Although these participants were recruited at different times after recovery, we were able to show a consistent result for MTB-stimulated IFN-γ SPUs as well as gene expression levels of OAS1, MAVS and SOCS3 between COVID-19 sub-groups in comparison with controls." (PMID 41468475, 2025). "All 11 showed decreased methylation in severe donors, suggesting that reduced DNA methylation near SOCS3 may contribute to upregulation of the gene in patients with severe COVID-19." (PMID 38238298, 2024). "We observed that COVID-derived PBMCs and monocytes showed significantly increased levels of receptor subunit Gp130, the receptor-associated kinase JAK2, STAT1, and STAT3, and the negative regulator SOCS3 (respectively) as a function of COVID-19 disease severity." (PMID 37310504, 2023). "Interestingly, the results were consistent with those in COVID-19; 27 of the IRGs were highly expressed in myeloid cells, except Icam1, Lyn, Cybb, Casp1, Gbp1, Vnn2, Socs3, Bcl2a1 and Lcn2 genes." (PMID 36817436, 2023). "Transcriptome studies have reported decreased levels of SOCS-3 in myeloid cells during COVID-19, which could lead to an immunosuppressive response to IL-6-mediated STAT3 activation during COVID-19." (PMID 35421120, 2022). "Consistent with previous publications 15-17, SARS-CoV-2 infection was also found to activate interleukin-6 (IL-6)-mediated signaling, which contributes to cytokine release syndrome in severe COVID-19, with representative genes of this pathway including SOCS3 and IL6." (PMID 34104087, 2021). "However, we found higher levels of OAS-1, MAVS and SOCS3 in COVID-19 cases as compared to HC group." (PMID 41468475, 2025).